CT45A1 (cancer/testis antigen family 45 member A1)
Diseases named in the same sentence as CT45A1 in open-access papers (continued):
Sharing a sentence is not in itself a finding about the gene and the disease.
cancer (22 papers, 2007 to 2025). A tumor composed of atypical neoplastic, often pleomorphic cells that invade other tissues. "Overexpression of CT45A1 was closely associated with poor prognosis in these cancer patients." (PMID 37924456, 2024). "This structure shields the inner CT45A1 (Low) cancer cells from targeted antibody therapy and potentially subsequent antitumor immunity, thereby driving aggressive MSI‐H CRC outcomes." (PMID 39322998, 2025). "Overexpression of CT45A1 enhances tumor cell motility and promotes cancer metastasis to the lungs and bones." (PMID 37924456, 2024). "Overall, the survival advantage of CT45A1‐expressing MSI‐H CRC cells during NK cell killing may not be a result of decreased activity of NK cells, highlighting that CT45A1 is a cancer‐autologous driver of NK cell resistance." (PMID 39322998, 2025). "The increased resistance to NK killing in CT45A1‐overexpressing CRC cells may be a result of intrinsic resistance of the cancer cells themselves or decreased cytotoxic activity of the cocultured NK cells." (PMID 39322998, 2025). "CT45A1‐expressing MSI‐H CRC cells, but not MSS CRC cells, exhibited enhanced resistance to NK cell cytotoxicity and generated homotypic cell‐in‐cell (CIC) structures with CT45A1‐expressing outer cells, protecting the inner cancer cells against therapeutic targeting." (PMID 39322998, 2025). "Additionally, the t-test showed a significant positive correlation between CT45A1 levels and pathological cancer grade (p < 0.001)." (PMID 37924456, 2024). "CT45A1 promoted tumorigenesis, neovascularization, cancer metastasis, and drug resistance." (PMID 37924456, 2024). "Furthermore, CT45A1 overexpression has been confirmed in various cancers with a weak tumorigenic effect." (PMID 35659630, 2022). "CT45A1 and is aberrantly overexpressed in various types of cancer." (PMID 33413474, 2021). "Moreover, the homotypic CIC structure of two cancer cells could be observed upon coculturing Venus‐carrying, CT45A1‐expressing MSI‐H CRC cells with mCherry‐carrying, vector‐expressing MSI‐H CRC cells." (PMID 39322998, 2025). "Despite the differences at the cellular level, both CT45A1‐positive MSI‐H CRC patients and CT45A1‐positive MSS CRC patients had worse survival outcomes, suggesting the presence of distinct mechanisms underlying CT45A1‐driven cancer malignancy in these two CRC subtypes." (PMID 39322998, 2025). "Treating HCT15‐CT45A1 cells with ML‐7 also decreased MLC2 phosphorylation and sensitized cancer cells to NK cell killing, suggesting that MLCK activation also occurs in CT45A1‐expressing CRC cells." (PMID 39322998, 2025). "It has been reported that CT45A1 plays a cancer-promoting role by triggering epithelial-mesenchymal transition (EMT) and cancer stem cell generation." (PMID 35651938, 2022). "Not surprisingly, several cancer testis antigens (CTA) including CT45A1, CT45A3, CT45A5, CTAG1B and CTAG2 were highly expressed in TNB-High or TMB-High tumors." (PMID 41562064, 2025). "Cancer/testis antigen-45A1 (CT45A1) is overexpressed in various types of cancer but is not expressed in healthy women." (PMID 37924456, 2024). "Cancer/testis antigen-45A1 (CT45A1) is a proto-oncogene overexpressed in various types of cancer; it is not expressed in normal tissues and cells in healthy women." (PMID 37924456, 2024). "Overexpression of CT45A1 increased cancer cell resistance to NK cell killing via the RHO‐ROCK/MLCK‐MLC2 signaling axis and promoted outer cell fate in homotypic CIC structures without affecting cancer cell motility in MSI‐H CRC cell lines." (PMID 39322998, 2025).
tumor (21 papers, 2011 to 2025). "Endogenous CT45A1High MSS/MSI‐H tumor organoids could be used in future studies to explore the molecular function of CT45A1 through a loss‐of‐function approach along with autologous or allogenic NK cells to optimize the treatment regimen." (PMID 39322998, 2025). "CT45A1 is a tumor intrinsic regulator that promotes aggressive behavior of MSI‐H CRC and poor clinical outcomes." (PMID 39322998, 2025). "Forty-five days later, the tumor volume and weight were significantly increased in the CT45A1 expression group compared to the control group." (PMID 37924456, 2024). "CT45A1 promotes tumor growth, neovascularization, and metastasis by promoting the expression of many tumorigenic genes and activating oncogenic signaling pathways." (PMID 37924456, 2024). "CT45A1 enhanced tumor growth, neovascularization, metastasis, drug resistance, and apoptosis resistance by up-regulation of various oncogenic genes and activation of key tumorigenic signaling pathways." (PMID 37924456, 2024). "To elucidate the presence and prognostic role of these factors and TAAs in HL we conducted NanoString analysis on primary tumor biopsies and found high expression of CT45A1, PRAME, Survivin, and other TAAs." (PMID 34584203, 2022). "Tumor formation assay in vivo revealed that tumors with overexpressed CT45A1 growth more rapidly and bigger that cells in control group which was further supported by the higher expression of Ki-67 in tumors with overexpressed CT45A1 by IHC." (PMID 34172717, 2021). "However, CT45A1, a highly expressed tumor antigen with a relatively low FDR among the other differentially expressed (DE) genes in the aggressive MSI‐H CRC tumors, was not annotated in the functional enrichment analysis." (PMID 39322998, 2025). "Additionally, we performed in vitro tube formation assay to assess the effect of CT45A1 on tumor cell-mediated neovascularization." (PMID 37924456, 2024). "In short, these data imply that CT45A1 enhances tumor malignant progression and neovascularization." (PMID 37924456, 2024). "Thus, inhibition of oncogenic CT45A1 expression is a new strategy for tumor suppression." (PMID 37924456, 2024). "Emerging studies have revealed that numerous CTAs, such as SSX (CTA5), CAGE-1 (CTA3), Piwil2 (CTA80), CT45A1, and the MAGE family gene MAGE-C2 (CTA10), induce EMT to promote tumor metastasis." (PMID 35347116, 2022). "Furthermore, the outer cell fate of CT45A1 (+) cells in a CIC structure was observed in MSI‐H CRC tumor sections, and MSI‐H CRC patients with upregulated CT45A1 expression exhibited increased MLC2 phosphorylation and poor clinical outcomes." (PMID 39322998, 2025). "H&E staining indicated that the number of blood vessels was increased 3.5-fold in the tumors with CT45A1 expression compared to the control tumors without CT45A1 expression, suggesting that CT45A1 enhances tumor growth." (PMID 37924456, 2024).
CT45A1 also shares sentences with these, for which no sentence is quoted: Hodgkins lymphoma (4 papers); myeloma (3); endometrial cancer (2); fibrosarcoma (2); classical Hodgkin's lymphomas (1); colon cancer (1); diffuse large B-cell lymphoma (1); gastric tumors (1); lung adenocarcinoma (1); multiple myeloma (1); plasmacytoma (1); serous ovarian cancer (1).